IGFL1 (IGF like family member 1)
Description:
Probable ligand of the IGFLR1 cell membrane receptor.
Synonyms: UNQ644; APRG644
Tractability: Antibody: UniProt places it where antibodies can reach, with high confidence; UniProt predicts a signal peptide or a membrane-spanning region; its Gene Ontology location is reachable by antibodies, with medium confidence.
Gene: Protein-coding gene on chromosome 19 (46,229,742 to 46,231,243, forward strand). Ensembl gene ENSG00000188293.
Subcellular location: Secreted
Gene Ontology:
Molecular function: protein binding; signaling receptor binding
Cellular component: extracellular region
Genetic constraint (gnomAD): Loss-of-function variants: 16 observed, 15.49 expected, observed/expected ratio (o/e) 1.03, 90% interval 0.7 to 1.56. The upper end of that interval is the gene's LOEUF score, 1.56, which puts it in group 6 of 6, group 1 being the genes least tolerant of losing a copy. Missense variants: 149 observed, 147.67 expected, observed/expected ratio (o/e) 1.01, 90% interval 0.88 to 1.16. Synonymous variants: 59 observed, 55.47 expected, observed/expected ratio (o/e) 1.06, 90% interval 0.86 to 1.32.
Homologues: Orthologues: chimpanzee IGFL1 (97% identical), macaque IGFL1 (90% identical). Paralogues in human: IGFL3 (42% identical), IGFL2 (40% identical), IGFL4 (32% identical).
Diseases named in the same sentence as IGFL1 in open-access papers:
IGFL1 is named in the same sentence as 14 diseases in open-access papers, as found by Europe PMC text mining. Sharing a sentence is not in itself a finding about the gene and the disease. The quoted sentences say what the papers report.
breast carcinoma (2 papers, 2023). "KLF5’s proliferative and pro-survival effects are mediated by IGFL2-AS1, and KLF5 promotes basal-like breast cancer by upregulating the expression of IGFL1 and cell growth and survival." (PMID 37893009, 2023).
colorectal cancer (1 paper, 2026). A primary or metastatic malignant neoplasm that affects the colon or rectum. "While insulin growth factor like family member 1 (IGFL1) has been implicated in the regulation of various diseases, its functional role in colorectal cancer remains poorly characterised." (PMID 41635856, 2026).
tumor (5 papers, 2022 to 2026). "Within the tumour microenvironment, IGFL1 appears to play a critical role in modulating the infiltration of diverse immune cell populations." (PMID 41635856, 2026). "The “platelet-derived growth factor binding” and “insulin-like growth factor binding” signatures were among the top signatures enriched and the respective genes PDGFRβ, PDGFRα, and IGFL1 were among the top-enriched genes in mCAFhighendotheliahigh tumor niches." (PMID 41083996, 2025). "Furthermore, IGFL1 expression patterns across distinct cellular subpopulations were examined using single-cell RNA sequencing datasets from the Tumor Immune Single-cell Hub (TISCH) database." (PMID 41635856, 2026). "The IGFL family has a similar protein structure and expression pattern to the IGF family, and previous reports have confirmed that IGFL2‐AS1 could promote IGFL1 expression in tumor cells." (PMID 36537608, 2023). "We performed qPCR on a subset of genes that were either among the most significant DEGs identified in our analysis of colon organoids of FAP versus healthy subjects and/or were significant in an analysis of either EOCRC tumor datasets: NKD1, EYA2, EGR2, EPDR1 and IGFL1." (PMID 36077675, 2022).
cancer (1 paper, 2022). A tumor composed of atypical neoplastic, often pleomorphic cells that invade other tissues. "IGFL1 has previously been proposed to be an oncogene in other cancers, where it was found to aid in cancer cell growth and survival." (PMID 36077675, 2022).
IGFL1 also shares sentences with these, for which no sentence is quoted: lung adenocarcinoma (2 papers); colon adenocarcinoma (1); dermatitis (1); gastric cancer (1); Hypertension (1); lung squamous cell carcinoma (1); psoriasis (1); pulmonary hypertension (1); rectum adenocarcinoma (1); uterine corpus endometrial carcinoma (1).